SS18 (SS18 subunit of BAF chromatin remodeling complex)
Diseases named in the same sentence as SS18 in open-access papers (continued):
Sharing a sentence is not in itself a finding about the gene and the disease.
epithelioid sarcoma (3 papers, 2022 to 2025). An aggressive malignant neoplasm of uncertain differentiation, characterized by the presence of epithelioid cells forming nodular patterns. "Taken together, the overall features were considered to be unclassified malignant cutaneous spindled and epithelioid sarcoma with a novel SS18::NEDD4 fusion gene." (PMID 35639915, 2022). "In summary, we report a unique case of previously unclassified cytokeratin positive malignant cutaneous spindled and epithelioid sarcoma with aggressive behavior, harboring an SS18::NEDD4 fusion." (PMID 35639915, 2022). "Herein, we describe an aggressively behaving malignant cutaneous spindled and epithelioid sarcoma harboring an SS18::NEDD4 gene fusion in a 60‐year‐old female." (PMID 35639915, 2022). "Herein, we report a case of an unclassified malignant cutaneous spindled and epithelioid neoplasm in a 60‐year‐old female that resembled an epithelioid sarcoma (ES) and harbored a rare SS18::NEDD4 gene fusion." (PMID 35639915, 2022). "These include MEF2C::SS18 in microsecretory adenocarcinoma of the skin and salivary gland, SS18::NEDD4 in cutaneous spindled and epithelioid sarcoma, SS18::POU5F1 in a primary renal undifferentiated round cell sarcoma and at least 6 cases of CRTC1::SS18 in undifferentiated round cell sarcomas." (PMID 40849585, 2025).
lung carcinoma (2 papers, 2022 to 2025). "Knowledge about the actual oncogenic signals effected by SS18-fusion protein in lung cancer is still limited." (PMID 36531058, 2022).
melanoma (2 papers, 2025 to 2026). A malignant, usually aggressive tumor composed of atypical, neoplastic melanocytes. "While Arid2 loss can result in genomic redistribution of BAF in melanoma, this is unlikely to occur in DMTF1 KD NSC given that DMTF1 loss down-regulates both Ss18 and Arid2 expression." (PMID 41481722, 2026).
ovarian carcinoma (2 papers, 2021 to 2024). A malignant neoplasm originating from the surface ovarian epithelium. "Other SWI/SNF altered cancers that are dependent on EZH2 include SS18-SSX translocated synovial sarcoma, ARID1A-mutated ovarian cancer, SMARCA4-mutated lung and ovarian cancers, and PBRM1-mutated renal cancers." (PMID 34617019, 2021). "Our results demonstrated that PRAME upregulation is triggered by direct binding of SS18-SSX to the PRAME promoter, in line with a previous report on SS18 in ovarian cancer." (PMID 39550391, 2024).
spindle cell neoplasm (2 papers, 2021 to 2022). A benign or malignant neoplasm characterized by the presence of neoplastic spindle cells. "The resected specimen confirmed margin-free excision of a monophasic spindle cell neoplasm invading the submucosa and presenting the rearrangement of SS18 gene at fluorescence in situ hybridization (FISH)." (PMID 33648512, 2021).
B-cell acute lymphoblastic leukemia (1 paper, 2022). A neoplasm of lymphoblasts committed to the B-cell lineage, typically composed of small to medium-sized blast cells. "Specifically, SS18 rearrangements involving the MEF2C and MEF2D partner genes, resulting in MEF2C::SS18 and MEF2D:SS18 gene fusions, have been identified in microsecretory adenocarcinoma and the B‐cell acute lymphoblastic leukemia, respectively." (PMID 35639915, 2022).
brain tumors (1 paper, 2024). "In vivo, mutation of the TEAD binding site of YAP in YAP::MAML2, YAP::MAMLD1, YAP::FAM118B, YAP::SS18, and YAP::TFE3 significantly reduced the oncogenic potential of these protein fusions to initiate brain tumors in mice." (PMID 40491864, 2024). "Working in vivo, multiple studies demonstrated that several YAP fusion proteins, such as YAP::FAM118B, YAP::MAML2, YAP::MAMLD1, YAP::SS18, and YAP::TFE3, can induce brain tumors and/or muscle tumors in mice." (PMID 40491864, 2024). "Mouse brain tumors formed from YAP::FAM118B, YAP::MAMLD1, or YAP::SS18 fusion protein expression showed distinct morphology and gene expressions profiles from brain tumors with the YAP::TFE3 fusion protein." (PMID 40491864, 2024).
carcinosarcoma (1 paper, 2015). A malignant tumor composed of a mixture of carcinomatous and sarcomatous elements. "More than 90 % of SS present this translocation, which gives rise to a fusion gene, SS18 (SYT)-SSX (SSX1 or SSX2, or both), whereas MPNST and carcinosarcoma lack SS18-SSX fusions." (PMID 26112006, 2015).
cardiac neoplasms (1 paper, 2026). "Accurate differentiation from other cardiac neoplasms requires immunohistochemistry and confirmation of the SS18-SSX gene fusion via fluorescence in situ hybridization (FISH)." (PMID 41938459, 2026).
epithelial-myoepithelial carcinoma (1 paper, 2021). A malignant neoplasm which occurs mostly in the major salivary glands (most frequently in the parotid gland), but also in the minor salivary glands of the oral mucosa and the tracheobronchial tree. "Of those, SSX2 and SS18 have been identified in histology-type investigations in the literature, whilst MVP2 function is little known, while HRAS is implicated in various types of cancers (i.e., salivary duct carcinoma, epithelial myoepithelial carcinoma, etc." (PMID 34359782, 2021).
mucoepidermoid carcinoma (1 paper, 2022). A carcinoma morphologically characterized the presence of cuboidal mucous cells, goblet-like mucous cells, squamoid cells, cystic changes, and a fibrotic stromal formation. "Similarly, CRTC1::MAML2 fusions have been described in mucoepidermoid carcinoma of various sites, whereas CRTC1::SS18 fusion has been implicated in a subset of undifferentiated small round blue cell sarcomas CMTCT have only been reported in CMTCT." (PMID 36726909, 2022).
salivary gland carcinoma (1 paper, 2024). A carcinoma that arises from the major or minor salivary glands. "A comprehensive study indicated that while FISH was performed on 4 MSA and 8 tissue microarrays (TMAs) containing 423 salivary gland carcinomas, all 4 MSA demonstrated classic split patterns on SS18 break-apart FISH, and other tumours were negative for SS18 rearrangement." (PMID 38982505, 2024).
undifferentiated sarcomas (1 paper, 2022). "Using the FISH technique, the 24 patients with rearranged SS18 were classified as SS, while the 12 cases with non-rearranged SS18 were reported as undifferentiated sarcomas." (PMID 36164527, 2022).
tumor (65 papers, 2010 to 2026). "In this study, the break-apart signal detected by FISH confirmed the association of the tumour with the SS18 gene." (PMID 38982505, 2024). "SS18::SSX associates with mammalian BAF complexes suggesting deregulation of chromatin architecture as the oncogenic driver in this tumour type." (PMID 38798672, 2024). "Mutations in mSWI/SNF subunits including ARID1A/B, BRG1, and SS18 are linked to multiple tumor types." (PMID 38326345, 2024). "SS18 was unique among the genes studied since it was the only one in which the mutation status was linked to Tumor Type (p=0.0137)." (PMID 36531058, 2022). "In SS, the expression of stem cell transcription factor SOX2 and its histone H3K27me3 triggered by mutations in the SS18-SSX driver caused tumor development." (PMID 35151264, 2022). "Although multiple lines of evidence suggest that the SS18/SSX fusion is the oncogene in this tumor, the protein expression profiles associated with SS18/SSX have yet to be elucidated." (PMID 30680066, 2018). "Several studies have reported that the SS18-SSX fusion gene is involved in tumor growth and progression by activating transcription, reorganizing chromatin, controlling cell cycle, and inhibiting apoptosis." (PMID 41422105, 2025). "These tumours are primarily defined by the SS18-SSX fusion oncogene, resulting from a t(X;18)(p11.2;q11.2) translocation." (PMID 41561516, 2025). "The tumour showed characteristic histopathological and immunohistochemical findings along with the SS18 gene rearrangement." (PMID 38982505, 2024). "Given the notorious difficulty to target the fusion protein itself, functional insights into SS18-SSX-shaped tumor biology are essential to decipher druggable tumor vulnerabilities." (PMID 35556229, 2022). "To further understand the biological processes and networks involved in tumor malignancy based on the proteins regulated by SS18/SSX, we performed network analyses using the Ingenuity Pathways Analysis (IPA) system (QIAGEN, Redwood City, CA, USA)." (PMID 30680066, 2018). "Formalin-fixed paraffin embedded (FFPE) patient-derived synovial sarcoma tumor samples were used to detect SS18-SSX/TLE1 co-localization in human tumor tissue samples." (PMID 27120803, 2016). "If the SS18–SSX fusion type is associated with survival outcomes, it should play an important role in tumor cell behavior, affecting its initiation, progression, and metastatic activity." (PMID 26217552, 2015). "Our results revealed the possibility that SS18-SSX is involved in tumor proliferation because of its interaction with some specific proteins interacting with the wild-type SSX via the SSX region of SS18-SSX." (PMID 24130893, 2013). "The presence of SSX2 expression in so many tumor types suggested that this antigen is upregulated in cancer independently from fusion events with SS18, perhaps by alterations in methylation status or by the overexpression of SSX2 transcriptional activators." (PMID 20981248, 2010). "Anti-HA staining confirmed nuclear expression of SS18::SSX in tumor cells." (PMID 40523919, 2025). "Mechanistically, TAK-981 de-SUMOylates the cBAF subunit SMARCE1, stabilizing and restoring cBAF on chromatin, shifting away from SS18::SSX-ncBAF-driven transcription, associated with DNA damage and cell death and resulting in tumor inhibition across both human and mouse SS tumor models." (PMID 38883782, 2024). "Moreover, we identified 14 tumor-specific gene fusion pairs in SS, which not only included the known gene fusions of SS18-SSX but also contained novel fusion events involving both protein-coding and lncRNA genes." (PMID 36118864, 2022). "In addition, detection of SS18 break-apart was performed by fluorescence in situ hybridization analysis, and the tumor was showed SS18 gene rearrangement." (PMID 35820955, 2022).
tumor (continued). "Accordingly, detailed understanding of the chromatin remodeling events that drive transcriptional changes at the binding sites of the fusion protein and their reversibility upon SS18-SSX depletion are critical toward identifying new tumor-specific therapeutic strategies." (PMID 33361335, 2021). "FISH revealed SS18 split signals in the tumor cells and the case was diagnosed as SS." (PMID 27068820, 2016). "They suggested that SS18 might influence the manifestation of the tumor since the SS18-SSX fusion protein is also localized in the nucleus and displays a similar punctated pattern." (PMID 24130893, 2013). "In the case of both genes, it was observed that the last 78 C-terminal amino acids of SSX1 and SSX2 replaced the last 8 amino acids of the C-terminus of SS18 in most tumors, however, alternate fusions were also observed less frequently for some tumor specimens." (PMID 20981248, 2010). "The SS18-SSX fusion protein functions as an aberrant transcription factor, disrupting normal gene expression and promoting tumour formation and growth." (PMID 41561516, 2025). "Our study provides novel insights into the multilayered regulation of key EMT players by SS18::SSX and BRD9 in SySa, thereby defining tumor phenotype and (potentially) prognosis." (PMID 41440042, 2025). "Genetic inhibition of SS18::SSX results in growth arrest and cell death in SS cells in vitro and inhibition of tumor growth in vivo." (PMID 38883782, 2024). "To uncouple SS18 and SSX-dependent activities, we started by mapping protein domains in SS18-SSX that are essential for tumor maintenance." (PMID 37735617, 2023). "Intriguingly, these tumor-specific gene fusion events contain one TF of SSX2 and seven oncogenes of SS18, SSX1, SSX2, BCOR, CNOT1, HIST2H2AC, and TOP1." (PMID 36118864, 2022). "In the development of this tumour type, a chromosomal translocation involving BAF subunit SS18 leads to the formation of an SS18-SSX fusion protein that displaces SMARCB1 in the BAF complex." (PMID 33941852, 2021). "Five neoplasms had different gene fusions including a neoplasm with FUS-CREM gene fusion, two SS with SS18- SSX gene fusion, two ASPS with TFE3-ASPSCR1 gene fusion, and one SFT with immunolabeling for STAT6 indicating a STAT6-NAB2 gene fusion (for details)." (PMID 34350470, 2021). "We have previously shown that SS18-SSX interacts with its partners at promoters recognized by ATF2, repressing transcription at critical tumor suppressor loci including EGR1 and CDKN2A." (PMID 28056055, 2017). "Studies on the MYF5-CRE SS18/SSX2 transgenic model of SS found that SS18-SSX2 aberrantly activates Wnt/β-catenin signaling and that genetic deletion of β-catenin blocks tumor formation." (PMID 26905812, 2016). "The resultant SS18-SSX fusion protein functions as an oncogene, affecting the regulation of transcription and chromatin remodeling, leading to uncontrolled cellular proliferation and tumor development." (PMID 40718269, 2025). "None of the blood samples with known synaptotagmin (SYT; SS18)::SSX family member 1/2 (SSX1/2) fusions in the primary tumour had detectable cfRNA." (PMID 39797974, 2025). "MSA consistently harbours recurrent MEF2C::SS18 fusions, which have not been previously reported in any human neoplasm." (PMID 38982505, 2024). "The resulting SS18-SSX fusion oncoprotein participates in both positive and negative regulation of gene expression, which subsequently leads to the activation of oncogenic pathways and the inhibition of tumour suppressor pathways." (PMID 39045458, 2024). "Fusion of SS18 to SSX generates an aberrant transcriptional regulator, which, in permissive cells, drives tumor development by initiating major chromatin remodeling events that disrupt the balance between BAF-mediated gene activation and polycomb-dependent repression." (PMID 33361335, 2021).
tumor (continued). "The function of the SS18-SSX chimeric protein and its relationship to tumor development remains unknown, as does the mechanism through which the translocation occurs." (PMID 30326929, 2018). "TLE1 co-localized in the nucleus with SS18-SSX (but not with wild-type SS18) in cell lines and in human tumor tissue, and these interactions were disruptable by treatment with histone deacetlyase inhibitors." (PMID 27732970, 2017). "Desmin, SMA, S100, CD31, Caldesmon, TLE-1, WT-1 and SS18 were negative in the tumor." (PMID 40831926, 2025). "Furthermore, on staining for the SS18::SSX fusion specifically obtained from in vivo tumor sections, we observed that TAK-981 treated tumors had a significant decrease in the percentage of cells with high SS18::SSX expression as assessed by immunohistochemistry compared to vehicle treated mice." (PMID 40804185, 2025). "Restoration of HDAC complexes in the condensates severely dampens the activation of SS18-SSX downstream genes such as PAX6 and NKX3-2 and almost abolishes the tumorigenicity of SS18-SSX tested by EdU cell proliferation assay, colony formation assay and tumor-bearing mouse models." (PMID 38678233, 2024). "Although SS18-SSX IHC in biopsy or cytology specimens from pulmonary metastatic SS was not assessed in this study, a differential diagnosis of SS could be made using small amounts of tumor tissue or cells obtained by bronchoscopy or imaging-guided biopsy." (PMID 34127031, 2021). "Recently, Kadoch described the high-affinity binding of SS18/SSX fusion to the core subunits of the SWI/SNF (BAF) complex and SS18 and SS18/SSX incorporate into the core subunits of SWI/SNF (BAF) complex, by dissociating BAF47 from the complex, thereby releasing SNF5, a tumor suppressor." (PMID 30680066, 2018). "However, in contrast to SSX1/2, RT-PCR data from 44 SS tumor samples revealed that SSX3 was not a fusion partner with SS18." (PMID 20981248, 2010). "In Case 1, the NUTM1 break-apart signal was observed in 84% of tumor cells, whereas the tumor was negative for BRD4::NUTM1, SS18, and EWSR1 rearrangements." (PMID 38239638, 2023). "During the first round of immunohistochemical stains, the tumor cells showed positivity for CD56, CD99 (diffuse to patchy), INSM1, and NKX2.2, while they were negative for desmin, cytokeratin, SS18-SSX, and WT-1." (PMID 36765856, 2023). "Immunohistochemistry showed benign epithelial positivity for cytokeratin and focal malignant stromal positivity for smooth muscle actin and CD10; however, the tumor was negative for CD99, Wilm's tumor protein, SS18-SSX, BCOR, and estrogen/progesterone receptors." (PMID 41681728, 2026). "Based on our findings, we can conclude that detection of the chimeric SS18-SSX fusion gene after surgical excision and/or chemotherapy/radiotherapy is a rare circumstance and hence in itself is not sufficient for monitoring the tumor recurrence." (PMID 30326929, 2018). "Additionally, the tumor was negative for most immunohistochemical markers (CKAE1/AE3, p63, CD23, CD21, MUC4, NUT, CDK4, Pan-TRK, STAT6, SS18, MDM2, Desmin, S100, ERG, TLE1, Fli) and showed only weak and most probably unspecific expression of CD99, CD56, and CD34." (PMID 39519042, 2024). "However, SS18(YA)-SSX mutant fails to activate the downstream genes and loses tumorigenicity based on EdU cell proliferation assay, colony formation assay and tumor-bearing mouse models, suggesting that the tyrosine-based condensation also plays a critical role in its tumorigenic potential." (PMID 38678233, 2024).
tumor (continued). "Though no drugs able to specifically target the SS18-SSX fusion oncoprotein are currently available, compounds able to disrupt its partnering interactions might be expected to reactivate normal gene transcription and elicit anti-tumor effects and clinical response." (PMID 28056055, 2017).